ANGPTL4 (angiopoietin like 4)
Diseases named in the same sentence as ANGPTL4 in open-access papers (continued):
Sharing a sentence is not in itself a finding about the gene and the disease.
nephrotic syndrome (23 papers, 2013 to 2026). A collection of symptoms that include severe edema, proteinuria, and hypoalbuminemia; it is indicative of renal dysfunction. "Angiopoietin-like protein 4 (ANGPTL4), found on the surface of podocytes, has been linked to nephrotic syndrome (NS) and plays a role in triggering proteinuria." (PMID 40968277, 2026). "Clement and colleagues demonstrated the critical role of podocyte-specific Angptl4 in causing proteinuria in nephrotic syndrome." (PMID 39630889, 2024). "Interesting, we also observed Dex strongly induced angiopoietin-like 4, a protein known to be a GR-responsive gene, but also one that has been previously associated with proteinuria and nephrotic syndrome." (PMID 23593176, 2013). "Angptl4 overproduction is associated with development of nephrotic syndrome, which can occur in subsets of diabetic patients." (PMID 24039874, 2013). "Recent studies suggest that ANGPTL4 may play a crucial role in the pathogenic mechanisms of nephrotic syndrome." (PMID 39840089, 2024). "However, in agreement with our finding, a study involving children with the minimal change disease, which is a common cause of the nephrotic syndrome, reported an overproduction of ANGPTL4 in the glomerulus (i.e., the filtering unit of the kidney)." (PMID 31772941, 2019). "Thus, our data suggest ANGPTL4 as a novel biomarker that can be employed as a predictive marker for a nephrotic syndrome risk." (PMID 31772941, 2019). "In conclusion, our study addressed the role of MIF and ANGPTL-4 in the pathogenesis and management of nephrotic syndrome, as well as their position as determinants of steroid responsiveness of glomerular diseases." (PMID 40968277, 2026). "In our research, which utilized human renal biopsy samples from individuals with primary nephrotic syndrome, we concentrated on the expression of ANGPTL4 in renal tissues post-massive proteinuria episodes." (PMID 39776814, 2025). "Future large-scale, multicenter clinical studies are needed to comprehensively assess the effectiveness and specificity of ANGPTL4 as a biomarker for nephrotic syndrome in blood and urine." (PMID 39840089, 2024). "Recent studies have reported that ANGPTL4 is upregulated in models of conditions such as IgA nephropathy, cisplatin-induced acute kidney injury, nephrotic syndrome, and diabetic nephropathy, promoting renal injury." (PMID 38992710, 2024). "Circulating ANGPTL4 levels increase in all forms of nephrotic syndrome and are mostly secreted from adipose tissue, skeletal muscle, the heart, and the liver." (PMID 37795536, 2023). "In nephrotic syndrome, angiopoietin-like 4 (ANGPTL4) is thought to play a role in hyperTG development." (PMID 34368411, 2021). "Considering ANGPTL-4 is a major molecular mediator of nephrotic syndrome, it has been identified as an ideal candidate for the treatment of proteinuric disorders caused by chronic kidney disease." (PMID 28978304, 2017). "Elevated plasma Angptl4 levels has been reported in patients with nephrotic syndrome due to MCD, FSGS, MN and crescentic glomerulonephritis compared to control subjects." (PMID 28441404, 2017). "Additional molecules including hemopexin, angiopoietin-like-4 and CD80 are associated with nephrotic syndrome and have also been shown to cause proteinuria in experimental animals but do not appear to be relevant to FSGS." (PMID 27104120, 2016). "Further investigation revealed two types of Angptl4 protein in nephrotic syndrome: (a) A hyposialylated form secreted from podocytes in MCD, and later also noted in glomeruli of Zucker Diabetic Fatty rats." (PMID 24611049, 2014). "Since circulating Angptl4 is a major molecular mediator of nephrotic syndrome due to a variety of glomerular diseases, it is an ideal candidate for a parenteral once-a-month therapeutic agent to treat proteinuric disorders that cause chronic kidney disease." (PMID 24611049, 2014).
nephrotic syndrome (continued). "In this study, we aimed to visualize the overall structure of podocytes in patients with primary nephrotic syndrome through immunostaining for ANGPTL4, which is either secreted by podocytes or derived from the blood circulation, thereby measuring podocyte morphology and assessing podocyte injury." (PMID 39776814, 2025). "Therefore, the potential mechanisms by which ANGPTL4 is involved in nephrotic syndrome require further investigation." (PMID 39840089, 2024). "For example, abnormal sialylation of ANGPTL4 was observed in nephrotic syndrome." (PMID 35461343, 2022). "Furthermore, podocytes secrete ANGPTL4 and mediate proteinuria in glucocorticoid-sensitive nephrotic syndrome." (PMID 34167540, 2021). "Further studies evaluating Angptl4 levels in serum and urine in a larger, more homogenous group of patients is needed before this could be recommended as a clinical biomarker for nephrotic syndrome." (PMID 31681707, 2019). "Recently, some evidence has shown that Angptl4 is involved in proteinuria in nephrotic syndrome." (PMID 25165975, 2014). "Future research should continue to explore the various forms of ANGPTL4 and their specific roles in nephropathy, with a particular focus on the clinical potential of sialic acid precursors and recombinant mutant ANGPTL4 as therapeutic strategies for nephrotic syndrome." (PMID 39840089, 2024). "To further confirm glomerular Angptl4 expression in MCD, we stained for Angptl4, desmin and synaptopodin in samples obtained from nephrotic syndrome patients with MCD (n = 15), MN (n = 5), FSGS (n = 5) and mesangial proliferative glomerulonephritis (MsPGN, n = 5)." (PMID 26352670, 2015).
ovarian carcinoma (23 papers, 2012 to 2025). A malignant neoplasm originating from the surface ovarian epithelium. "Two studies showed that increased ANGPTL4 was associated with increased resistance to both cisplatin and carboplatin in ovarian cancer." (PMID 40233044, 2025). "ANGPTL4 expression has been linked to chemotherapy resistance in pancreatic cancer, glioblastoma, and ovarian cancer, and is also linked to anoikis resistance and cancer progression." (PMID 40233044, 2025). "The aim of this investigation was to explore the involvement of ANGPTL4, which is associated with hypoxia, in the proliferation and migration of ovarian cancer (OC) cells." (PMID 38311733, 2024). "The expression of hypoxia-associated ANGPTL4 in human ovarian cancer was examined by bioinformatics analysis of TCGA and GEO datasets." (PMID 38311733, 2024). "Both Lep and Angptl4 are involved in the regulation of lipid metabolism and have been implicated in ovarian cancer tumorigenesis." (PMID 37375634, 2023). "Previous studies reported that high ANGPTL4 expression was detected in ovarian cancer xenograft mouse models and patients and was associated with shorter relapse-free survival times in serous ovarian carcinoma." (PMID 33726754, 2021). "As VEGFR2 Y949 plays an important role in tumor vascularization and growth, this tyrosine (Y) in VEGFR2 was mutated to phenylalanine (F) and spontaneous ovarian carcinoma was induced in siANGPTL4-injected mice to further determine the connection between ANGPTL4 and VEGFR2 pY949 in tumors." (PMID 33726754, 2021). "ANGPTL4 promotes angiogenesis, invasion, and metastasis, and its silencing in ovarian cancer cells has been shown to delay tumor progression." (PMID 37375634, 2023). "ANGPTL4 is regulated by peroxisome proliferator-activated receptor γ (PPARγ), who has been observed to be significantly increased in malignant ovarian tumours (grade 1, 2 and 3) compared to benign and borderline tumours." (PMID 37388244, 2023). "ANGPTL4 can combine with integrin α5β1 on the surface of ovarian cancer cells to induce drug resistance." (PMID 36247876, 2022). "Transduced A2780 and CAOV3 ovarian cancer cells were then xenografted into nude mice to identify the roles of ANGPTL4 in ovarian tumorigenesis in vivo." (PMID 33726754, 2021). "Here, we show that specific blockade of ANGPTL4-induced tumor angiogenesis results in inhibition of ovarian cancer cell proliferation and tumor growth in vivo." (PMID 33726754, 2021). "Western blot, quantitative reverse transcription PCR, and immunofluorescence analyses were applied to evaluate ANGPTL4 expression in ovarian cancer cell lines." (PMID 33726754, 2021). "While we did not investigate the connection between ANGPTL4 and VEGF in neoangiogenesis, our data suggest the proangiogenic role of ANGPTL4 in epithelial ovarian cancer, in which it increases tumor neovascularization and supports tumor growth and metastasis." (PMID 33726754, 2021). "A recent study using integrative genomic analysis demonstrated that in human ovarian cancer cells, ANGPTL4 is a direct target gene of Tafazzin (TAZ), which is another key transcriptional coactivator of the Hippo pathway." (PMID 34773076, 2021). "The aims of the current study were to determine ANGPTL4 expression in ovarian cancer cell lines and the effects of ANGPTL4 knockdown by RNA interference (RNAi) on cancer cell lines and tumors in vivo and in vitro." (PMID 33726754, 2021). "Inactivation of VEGFR2 Y949 phosphorylation in MISIIR-TAg VEGFR2Y949F/Y949F mice abolished all tumor-suppressive effects of ANGPTL4 inhibition in spontaneous ovarian carcinoma." (PMID 33726754, 2021). "A similar mechanism is described in ovarian cancer cells, where the loss of cell–cell contacts leads to the activation of TAZ, which induces Angiopoietin-like 4 protein (ANGPTL4) that sensitizes ferroptosis by activating the NADPH oxidase 2 (NOX2)." (PMID 34439395, 2021).
ovarian carcinoma (continued). "Additionally, as a regulator of lipid metabolism, ANGPTL4 reprograms lipid metabolism and promotes ovarian cancer metastasis." (PMID 40616161, 2025). "Furthermore, TAZ also upregulates NOX2 through angiopoietin-like 4 (ANGPTL4), a direct target gene of TAZ, thereby increasing susceptibility to ferroptosis in ovarian cancer cells." (PMID 40619484, 2025). "Furthermore, ANGPTL4 plays a role in ovarian cancer induced mesothelial cell migration and mesothelial to mesenchymal transformation, alongside promoting mesothelial cell induced ovarian cancer proliferation, migration, cell adhesion, and invasion." (PMID 40233044, 2025). "ANGPTL4 plays an essential role in the carboplatin resistance of ovarian cancer." (PMID 36247876, 2022). "The induction of drug resistance by ANGPTL4 has been reported in ovarian cancer." (PMID 36247876, 2022). "Furthermore, previous studies have shown that two proteins, PDZ-binding motif (TAZ) and testisin, inhibit ovarian cancer metastasis and that ferroptosis and chemoresistance are also related to ANGPTL4 inhibition." (PMID 33726754, 2021). "With the intensifying investigation of antiangiogenic therapies, research targeting ANGPTL4 may offer a strategy with great potential in future drug development to reduce the tumor burden and to improve therapeutic efficacy in ovarian cancer." (PMID 33726754, 2021). "In addition, ANGPTL4 expression induces the resistance of ovarian cancer to carboplatin through ANGPTL4." (PMID 34708125, 2021). "Moreover, fewer EdU-positive cells and lower EMT marker (slug and snail) expression were observed in A2780 and CAOV3 tumors with ANGPTL4 knockdown, indicating inhibition of ovarian cancer cell proliferation and invasion." (PMID 33726754, 2021). "Additionally, the mechanisms of ANGPTL4 inhibition in ovarian cancer were elucidated by using VEGFR2Y949F/Y949F and MISIIR-TAg spontaneous epithelial ovarian carcinoma mouse models." (PMID 33726754, 2021). "Our findings necessitate the exploration of the role of ANGPTL4 in different cancers such as glioblastoma, lower grade glioma, renal cell carcinoma, lung adenocarcinoma, lung squamous cell carcinoma, ovarian carcinoma, and rectal adenocarcinoma, as targeting ANGTPL4 could be of therapeutic benefit." (PMID 40233044, 2025). "However, whether ANGPTL4 deletion has clinical benefit in ovarian cancer therapy is unknown, and the related molecular mechanisms are obscure." (PMID 33726754, 2021). "However, the roles of ANGPTL4 in angiogenesis and tumor growth in epithelial ovarian cancer, the most lethal gynecologic malignancy, remain unclear." (PMID 33726754, 2021). "ANGPTL4 not only regulates vascular biology but also is related to other cellular metabolic processes, such as lipid metabolism; thus, whether ANGPTL4 inhibition affects biological processes in ovarian cancer cell lines (A2780 and CAOV3) was investigated." (PMID 33726754, 2021). "The current study developed a predictive model of CSOARG for prognosis in ovarian cancer using eight key genes (WNK1, ANGPTL4, AREG, IGF1, CXCL10, GMPR, FANCB, LYG1)." (PMID 40510161, 2025). "The significant correlation between ANGPTL4 and TAZ expression is unveiled by the TCGA ovarian cancer dataset, and the regulatory region of ANGPTL4 is physically associated with the YAP/TAZ/TEAD complex." (PMID 36247876, 2022). "In ovarian cancer, TAZ regulates the level of its direct target gene angiopoietin-like 4 (ANGPTL4) to manage the activity of NADPH oxidase 2 (NOX2), finally leading to ferroptosis." (PMID 36090052, 2022). "In ovarian carcinoma cell lines, TAZ upregulates NOX2 expression via increased induction of ANGPTL4 (angiopoietin-like protein 4)." (PMID 34572111, 2021). "ANGPTL4 expression was measured in human ovarian clear cell carcinoma ES2, human ovarian carcinoma A2780 and NCI/ADR-RES, and human ovarian adenocarcinoma COC1, SKOV3, OVCAR3, and CAOV3 cells." (PMID 33726754, 2021).
ovarian carcinoma (continued). "Our results show that the expression of ANGPTL4 is different in several ovarian cancer cell lines and that A2780 and CAOV3 cells have the highest expression of ANGPTL4." (PMID 33726754, 2021). "Silencing ANGPTL4 reduces A2780 and CAOV3 tumor growth, angiogenesis, and metastasis in vivo but not in vitro, indicating that ANGPTL4 is essential for tumor proliferation and vascular angiogenesis in ovarian cancer." (PMID 33726754, 2021). "Transwell assays demonstrated that silencing ANGPTL4 did not affect the migration and invasion abilities of ovarian cancer cells." (PMID 33726754, 2021). "In addition, ANGPTL4 is highly expressed in A2780 and MISIIR-TAg-induced ovarian carcinoma cells and in CAOV3 and OVCAR3 ovarian adenocarcinoma cells; however, the low to negligible levels of ANGPTL4 in other types of ovarian tumors limit these conclusions." (PMID 33726754, 2021). "Our results indicated that ANGPTL4 silencing did not inhibit ovarian cancer cell metastasis in vitro." (PMID 33726754, 2021). "Here, we demonstrated that ANGPTL4 was overexpressed in A2780 and CAOV3 ovarian cancer cells." (PMID 33726754, 2021). "Although no alterations in the migration, invasion, and proliferation abilities of ANGPTL4 knockdown A2780 and CAOV3 ovarian cancer cells were observed in our in vitro experiments, further studies to determine the impact that ANGPTL4 may have on ovarian cancer cell metabolism will be interesting." (PMID 33726754, 2021). "In vitro assays indicated that inhibition of ANGPTL4 by lentiviral small interfering RNA does not alter ovarian cancer cell proliferation, migration, invasion, and EMT, while ANGPTL4 silencing exhibited significant inhibitory effects on tumor angiogenesis, growth, and metastasis in vivo." (PMID 33726754, 2021).
Hepatic steatosis (20 papers, 2012 to 2025). Steatosis is a term used to denote lipid accumulation within hepatocytes. "Despite these constraints, the study has several strengths: to our knowledge, it is the first to assess the independent and joint associations of ANGPTL4 with glycemic status and hepatic steatosis, and it enrolled a larger sample than prior investigations." (PMID 41226996, 2025). "To further evaluate the relationships among glycemic status, hepatic steatosis, and serum ANGPTL4 concentrations, we performed multivariable linear regression." (PMID 41226996, 2025). "Serum ANGPTL4 levels were measured, and multivariate linear regression analysis was used to evaluate the relationship between ANGPTL4, glycemic status and hepatic steatosis." (PMID 41226996, 2025). "Insulin and ANGPTL4 are key, opposing regulators of LPL activity, insulin enhances LPL, whereas ANGPTL4 inhibits it, and LPL activity is closely linked to circulating free fatty acid levels and the development of hepatic steatosis." (PMID 41226996, 2025). "Third, the cross-sectional design precludes causal inference regarding the relationships among circulating ANGPTL4, glycemic status, and hepatic steatosis." (PMID 41226996, 2025). "Accordingly, this study aims to quantify the independent effects of glycemic status and hepatic steatosis on circulating ANGPTL4 concentrations and to assess their potential interaction." (PMID 41226996, 2025). "Taken together, while HFREP1 and Fetuin-A provide informative hepatic and systemic signals of metabolic stress, our data indicates that ANGPTL4 is elevated in glucose intolerance independently of hepatic steatosis." (PMID 41226996, 2025). "ANGPTL4 overexpression leads to reduced adiposity at the expense of increased liver steatosis and can therefore be considered as having both positive and negative effects on NASH." (PMID 35269515, 2022). "Transgenic mice with adipose tissue-specific Angptl4 overexpression exhibited glucose intolerance and impaired insulin sensitivity in skeletal muscle, as well as aggravated hepatic steatosis when subjected to long-term HFD feeding." (PMID 34944728, 2021). "Therefore, this study aimed to quantify the independent effects of glucose intolerance and hepatic steatosis on circulating ANGPTL4 concentrations." (PMID 41226996, 2025). "One study reported lower ANGPTL4 concentrations in adults with hepatic steatosis compared with healthy controls, positing that reduced ANGPTL4 leads to disinhibition of LPL, enhanced hydrolysis of circulating triglycerides, and increased free fatty acid flux to the liver." (PMID 41226996, 2025). "We found that IGT and NDD were independently associated with higher serum ANGPTL4 concentrations, irrespective of hepatic steatosis." (PMID 41226996, 2025). "ANGPTL4 overexpression in either normal chow diet-fed mice or high fat diet-fed mice reduced the weight of adipose tissue but increased liver steatosis and elevated plasma triglycerides, free fatty acids, glycerol, total cholesterol and high-density lipoprotein cholesterol." (PMID 30374329, 2018). "Serum ANGPTL4 concentrations were 11.2 ± 5.4, 11.7 ± 16.7, 23.8 ± 11.9, 29.6 ± 26.9, 10.9 ± 5.8, 14.3 ± 14.5, 20.4 ± 7.9, 25.0 ± 10.9 ng/mL in subjects with NGT, IFG, IGT, NDD, NGT + hepatic steatosis, IFG + hepatic steatosis, IGT + hepatic steatosis, NDD + hepatic steatosis, respectively." (PMID 41226996, 2025). "Moreover, among those with glucose intolerance, ANGPTL4 concentrations were comparable between participants with and without hepatic steatosis." (PMID 41226996, 2025). "Therefore, the effect of ANGPTL4 on NAFLD can be explained as being both positive and negative: increasing liver steatosis and decreasing adiposity." (PMID 30374329, 2018).